MPO (myeloperoxidase)
Diseases named in the same sentence as MPO in open-access papers (continued):
Sharing a sentence is not in itself a finding about the gene and the disease.
coronary atherosclerosis (12 papers, 2012 to 2025). Atherosclerosis of the coronary vasculature. "MI is a manifestation of coronary atherosclerosis, which has been reported to be associated with elevated plasma biomarkers of NETs such as double-stranded DNA, nucleosomes, and myeloperoxidase–DNA complexes." (PMID 30992036, 2019). "Some human studies also demonstrated that markers of NETs, such as nucleosomes and myeloperoxidase (MPO)–DNA complexes, are increased in patients with severe coronary atherosclerosis and predict risk of cardiac events." (PMID 36979845, 2023). "To explore the contribution of neutrophils to aortic sinus and coronary artery atherosclerosis in these mice, we stained aortic sinus and myocardial sections for the neutrophil marker, MPO as well as for Cit-H3, a marker of neutrophil extracellular traps (NETs)." (PMID 40403091, 2025). "Recent evidences have suggested that elevated level of myeloperoxidase from neutrophils could contribute to coronary atherosclerosis." (PMID 33676400, 2021). "Recent evidences indicated that elevated level of myeloperoxidase from the neutrophil could give rise to coronary atherosclerosis." (PMID 32247314, 2020). "MPO levels have been reported to be related to coronary atherosclerosis in Blacks, but not in Whites or Hispanics, demonstrating an important modifying role of black ethnicity on the association of MPO levels with CAD." (PMID 26754611, 2016).
Goodpasture’s syndrome (12 papers, 2001 to 2024). "These antibodies are a hallmark of anti-neutrophil cytoplasmic antibody (ANCA)-associated vasculitides (anti-MPO and PR3) and Goodpasture’s syndrome (anti-GBM)." (PMID 33263103, 2020). "We present here the case of a 27-year-old immunocompetent patient who developed pulmonary-renal syndrome, manifested with lung cavitation, miliary nodules, and necrotizing glomerulonephritis accompanied by elevated titers of myeloperoxidase antibody." (PMID 30131924, 2018). "We reviewed six similar cases reported in the literature and concluded that Goodpasture’s syndrome with pre-existing interstitial pneumonia and myeloperoxidase anti-neutrophil cytoplasmic antibody is related to a poor prognosis." (PMID 28403904, 2017). "We report a case of Goodpasture’s syndrome complicated with pre-existing chronic interstitial pneumonia and positive myeloperoxidase anti-neutrophil cytoplasmic antibody." (PMID 28403904, 2017). "The association of MPA with MPO-ANCA is reported to be in the range of 40–80%, and MPA with MPO-ANCA is noted to be frequently associated with necrotizing glomerulonephritis and/or pulmonary capillaritis, namely, a pulmonary-renal syndrome similar to that observed in Goodpasture syndrome or WG." (PMID 20981310, 2010). "The spectrum of MPO-ANCA positive interstitial pneumonia is multifaceted, from isolated lung involvement to pulmonary-renal syndrome." (PMID 38445024, 2024). "Our case was unique in that both MPO and PR3 positivity was seen together in the setting of statin use, along with the simultaneous presence of Goodpasture syndrome as well." (PMID 36419545, 2022). "In contrast, the main autoantigenic target of P-ANCA is myeloperoxidase (MPO) and such ANCA have been demonstrated in patients with MPA, EGPA and less frequently in Goodpasture's syndrome patients." (PMID 23241527, 2012).
hemorrhage (12 papers, 2011 to 2026). Loss of blood from the vascular compartment to the exterior or into nonvascular body space as a result of rupture or severance of the blood vessels. "After trauma-hemorrhage, MPO activity was significantly increased in vehicle-treated rats compared with sham-operated animals." (PMID 23285267, 2012). "Administration of the p38 MAPK inhibitor SB-203580 prevented the tropisetron-mediated attenuation of hepatic MPO activity after trauma-hemorrhage." (PMID 23285267, 2012). "After trauma-hemorrhage, MPO activity was increased significantly in vehicle-treated rats compared with sham-operated animals." (PMID 22022464, 2011). "Administration of the PI3K inhibitor wortmannin prevented the astringinin-mediated attenuation of hepatic MPO activity after trauma-hemorrhage." (PMID 22022464, 2011). "CINC-1 and CINC-3 levels also correlate with tissue MPO activity, a marker of neutrophil infiltration, after trauma-hemorrhage." (PMID 22022464, 2011). "The MPO-ANCA antibodies could lead to pulmonary capillaritis which might result in (subclinical) alveolar hemorrhage and finally fibrosis." (PMID 26266064, 2015). "Furthermore, administration of the p38 MAPK inhibitor SB-203580 prevented the osthole-mediated attenuation of hepatic MPO activity after trauma-hemorrhage [0.453±0.039 (osthole + SB-203580) vs. 0.277±0.023 (osthole) U/mg protein, p<0.05]." (PMID 23755293, 2013). "Furthermore, administration of the PPARγ antagonist GW9662 prevented the maraviroc-mediated attenuation of hepatic MPO activity after trauma-hemorrhage." (PMID 24205332, 2013). "The effects of these treatments were then examined with respect to hepatic injury as well as hepatic myeloperoxidase (MPO) activity, ICAM-1, IL-6, and phospho (p)-p38 MAPK/p38 MAPK levels following trauma-hemorrhage." (PMID 23755293, 2013). "MPO activity is an indicator of neutrophil activation, and it has been correlated with tissue ICAM-1 expression after trauma-hemorrhage." (PMID 24205332, 2013). "Tissue MPO activity is an indicator of neutrophil infiltration, and it has been correlated with ICAM-1 expression after trauma-hemorrhage." (PMID 23755293, 2013). "The effects of these treatments were then examined with respect to hepatic injury as well as hepatic myeloperoxidase (MPO) activity, intercellular adhesion molecule-1 (ICAM-1), interleukin-6 (IL-6), and PPARγ levels following trauma-hemorrhage." (PMID 24205332, 2013). "Tissue MPO activity is an important indicator of neutrophil infiltration, and it has been correlated with CINC-1 and CINC-3 expression after trauma-hemorrhage." (PMID 23285267, 2012). "Interestingly, the reinfection group with the lower dose (RE 25) stands out as the peak of hemorrhage, protein content, EPO, and MPO activity." (PMID 39621794, 2024). "In this study, our results indicate that trauma-hemorrhage results in a significant increase in hepatic pro-inflammatory cytokine/chemokine levels and ICAM-1 expression, which are accompanied with increased hepatic MPO activity." (PMID 22022464, 2011).
Hypercholesterolemia (12 papers, 2011 to 2024). An increased concentration of cholesterol in the blood. "This study identifies a significant association between total plasma cholesterol levels and MPO in patients affected by Familial Hypercholesterolemia and suggests the possibility of modulating MPO plasma concentration by cholesterol levels." (PMID 22014237, 2011). "This study conducted an analysis of an association of vascular endothelial function, NOx content, and cGMP level with vascular MPO activity in the hypercholesterolemia group and the PIO intervention group." (PMID 32190383, 2020). "In this sense, the present work showed an increase in MPO activity in the control group hypercholesterolemia (HC)." (PMID 30781884, 2019). "In hypercholesterolemia, there is elevated production of neutrophils, which display increased mobilization from the bone marrow, circulating in a prime state characterized by enhanced responsiveness of ROS and MPO to secondary stimuli." (PMID 39403884, 2024). "Among the mechanisms that may explain the link between hypercholesterolemia and increased OS is the higher MPO activity, an enzyme involved in ROS production and atherosclerotic plaque development." (PMID 34945165, 2021). "It suggested that PIO might improve vascular endothelial dysfunction in hypercholesterolemia by regulating vascular MPO activity via the NO/cGMP/cGK signaling pathway." (PMID 32190383, 2020). "We analyzed the association of vascular endothelial function and key signaling molecules (NOx and cGMP) of the NO/cGMP/cGK pathway with MPO activity to explore whether MPO played a role in vascular endothelial dysfunction in hypercholesterolemia." (PMID 32190383, 2020). "Similarly, during hypercholesterolemia, neutrophils showed a primed state characterized by elevated ROS production, increased release of myeloperoxidase (MPO) and increased expression of CD11b." (PMID 29515456, 2018). "Among FH patients, high MPO concentration further supports the hypothesis that hypercholesterolemia is a strong pro-inflammatory condition." (PMID 22014237, 2011). "Therefore, we studied MPO concentration in subjects with Familial Hypercholesterolemia (FH) undergoing LDL (Low Density Lipoprotein) apheresis (LDL-A) treatment." (PMID 22014237, 2011). "However, whether PPARγ agonists can restore NO bioavailability by regulating MPO, thereby improving vascular endothelial function and delaying the progression of atherogenesis in hypercholesterolemia, have not been confirmed." (PMID 32190383, 2020). "We also aimed to further observe whether PPARγ agonists could reverse vascular endothelial dysfunction in hypercholesterolemia and, if possible, to determine whether or not this was related to the regulation of vascular MPO and subsequent restoration of NO bioavailability." (PMID 32190383, 2020).
membranous nephropathy (12 papers, 2012 to 2024). "Membranous nephropathy associated with Hashimoto’s thyroiditis is well described in literature, but membranous nephropathy associated with crescents and MPO antibodies in the presence of Hashimoto’s thyroiditis is very rare." (PMID 25121358, 2014). "More interestingly, many studies suggested that MPO may be involved in IC formation and conversion into membranous nephropathy in some AAV cases, which are caused by immune mechanisms including immune-complex formation and pauci-immune mechanism." (PMID 36000886, 2022). "Myeloperoxidase ANCA-associated GN (MPO-ANCA GN) with membranous nephropathy (MN), where bright granular capillary MPO and IgG staining along the glomerular basement membrane (GBM) is present, has been reported; however, its clinicopathological features remain unclear." (PMID 39081744, 2024). "Membranous nephropathy with crescents secondary to Hashimoto’s thyroiditis and positive MPO represents dual glomerulopathy from 2 separate autoimmune processes due to a single underlying disorder." (PMID 25121358, 2014). "Myeloperoxidase anti-neutrophil cytoplasmic antibody-associated glomerulonephritis (MPO-ANCA-GN) and concurrent membranous nephropathy (MN) are very rare combination." (PMID 23537120, 2013). "Furthermore, myeloperoxidase and IgG were partially colocalized via double immunofluorescence; thus, MPO may be involved in IC formation and conversion into membranous nephropathy in some AAV cases." (PMID 36000886, 2022). "Serology indicated a significant presence of ANA or MPO-ANCA antibodies in patients with nephritic syndrome and the absence of PLA2R antibodies in patients with membranous nephropathy." (PMID 32466285, 2020).
Pulmonary hemorrhage (12 papers, 2012 to 2026). Pulmonary hemorrhage is a bleeding within the lungs. "In other experimental models, the presence of MPO-ANCA has been shown to cause pulmonary hemorrhage." (PMID 36975372, 2023). "In support of the pathogenetic role of ANCA, a case of neonatal pulmonary hemorrhage secondary to transplacental passage of MPO-ANCA by the mother has been well described." (PMID 36975372, 2023). "Co-injection of recombinant Rv0888NS/MS with an MPO inhibitor remarkably decreased recombinant Rv0888NS/MS-induced pulmonary hemorrhage, infiltration of inflammatory cells, and release of inflammatory cytokines (IL-6, TNF-α and IL-1β)." (PMID 29670633, 2018). "Compared with pulmonary hemorrhage in wild-type mice, in EC-SOD-deficient mice 1 h after pulmonary hemorrhage neutrophil aggregation, myeloperoxidase activity was increased 3.9 times, and NF-κB and lipid peroxidation enzyme activity was increased by 1.5 times." (PMID 30185231, 2018). "We report a case of hydralazine-induced pulmonary hemorrhage and pauci-immune crescentic glomerulonephritis with positive MPO, PR3 ANCAs, and anti-histone antibody." (PMID 25210633, 2014). "As such, we found a higher frequency of pulmonary haemorrhage among younger men and a higher frequency of ANCA and anti-GBM double positivity in older women, with a preponderance of MPO-ANCA." (PMID 38186880, 2024).
emphysema (11 papers, 2013 to 2025). "We describe three cases presenting with recurrent pulmonary haemorrhage, who develop anti myeloperoxidase antibodies (MPO) positivity and radiologically, cystic areas resembling emphysema many years after their first presentation." (PMID 31651292, 2019). "A recent in vivo study has suggested a prominent role of MPO in the pathogenesis of COPD including progression of emphysema, pulmonary hypertension, and small airway remodeling." (PMID 23637811, 2013). "However, this inflammatory response can lead to tissue damage, as neutrophils release proteolytic enzymes, such as neutrophil elastase and myeloperoxidase, which degrade extracellular matrix components, resulting in emphysema and airway remodeling." (PMID 40244222, 2025). "This indicates a crucial role of MPO in emphysema development." (PMID 35784687, 2022). "Since neutrophil infiltration plays an important role in emphysema development, we examined neutrophil activation by measuring intracellular and extracellular activity of the neutrophil granule protein myeloperoxidase (MPO)." (PMID 33301419, 2021). "However, we did not observe significant changes between WT and Duox1–/– mice with respect to overall neutrophil content during PPE-induced emphysema, based on intracellular MPO analysis, or with respect to induction of Cxcl1 mRNA." (PMID 33301419, 2021). "At 11 years from initial presentation, MPO-ANCA positivity was identified, and emphysema with a peribronchovascular distribution was observed on CT, with subsequent significant increase in extent." (PMID 31651292, 2019). "Here we describe three cases presenting with recurrent pulmonary haemorrhage, initially classified as IPH, who, several years after first presentation, develop anti myeloperoxidase antibodies (MPO) positivity, emphysema on CT and, in one case, renal involvement." (PMID 31651292, 2019). "Encouragingly, we verified various well-known mechanistic changes associated with emphysema development, such as NF-κB signaling and TLR4 signaling, as well as increased levels of TNF-α, CSF2, and non-predicted but related interleukins, MPO, and MMP-9 by means of proteomic analysis." (PMID 25962837, 2015). "Furthermore, one of the most intriguing findings of our study was the identification of a higher proportion of CPFE ANA + patients that also exhibited positive ANCAs (n = 7/40, 17.5%) against MPO compared to IPF patients without emphysema (n = 0) (p < 0.05)." (PMID 23697753, 2013).
fibrosis (11 papers, 2012 to 2025). the formation of excess fibrous connective tissue in an organ or tissue in a reparative or reactive process. "We then studied the expression of myeloperoxidase and Masson staining and show comparable colon neutrophil infiltration and fibrosis in C-HIV and P-HIV." (PMID 38016163, 2024). "Overall, these data suggest that MPO may promote the progression of NAFLD towards more advanced stages with fibrosis." (PMID 23285030, 2012). "Regarding the laboratory, imaging, and biopsy criteria, the most often met item was fibrosis or ILD on chest imaging (76.7%), followed by MPO-ANCA (or P-ANCA) positivity (24.1%)." (PMID 40361918, 2025). "We found that both NE and MPO were increased in BALF from bleomycin-treated mice relative to saline-treated mice, suggesting that neutrophils in fibrosis release more granules." (PMID 36534439, 2022). "Several biomarkers such as CRP, MPO-ANCA, and KL-6, BVAS, and PFT findings were not different between survivors and non-survivors of MPO-ANCA positive MPA-ILD, whereas bilateral lower lobe fibrosis scores were significantly higher in the non-survivors." (PMID 33452394, 2021).
hyperlipidemia (11 papers, 2018 to 2025). "The main finding of our study is that haemolysis and lipemia interfere with both MPO and RES BioVendor ELISA measurement." (PMID 31015785, 2019). "The aim of our study was to investigate the influence of haemolysis and lipemia on resistin (RES) and myeloperoxidase (MPO) measurement by BioVendor enzyme-linked immunosorbent assays (ELISA)." (PMID 31015785, 2019). "Therefore, the aim of our study was to investigate the influence of haemolysis and lipemia on both RES and MPO measurement by BioVendor enzyme-linked immunosorbent assays (ELISA)." (PMID 31015785, 2019). "Nevertheless, since this is the first report regarding haemolysis and lipemia on RES and MPO ELISA measurement we believe it provides evidence based approach to handling haemolysed and lipemic samples and adds valuable contribution to future experiments." (PMID 31015785, 2019). "Unfortunately, literature data regarding the influence of haemolysis and lipemia on MPO measurement is absent." (PMID 31015785, 2019). "Our results show that for BioVendor ELISA methods, haemolysis causes a positive bias both for MPO and RES, while lipemia causes negative bias for RES and positive bias for MPO up to 38.23 mmol/L triglycerides." (PMID 31015785, 2019). "Here, we demonstrate for the first time in humans that a single HFM sufficient to induce lipemia promotes RBC remodeling, induces intracellular ROS and oxidative damage to RBC membranes, and increases circulating and RBC-bound MPO that is sufficient to promote oxidative modification of HDL." (PMID 29572498, 2018).
IgA nephropathy (11 papers, 2011 to 2024). "We herein describe an unusual case of PTU-associated renal disease, with antibodies detected in the serum directed against MPO, PR3 and GBM, accompanied by histological evidence of IgA nephropathy and a tubulointerstitial infiltrate rich in IgG4-positive cells." (PMID 32703233, 2020).
ileitis (11 papers, 1993 to 2024). "TNBS ileitis caused a marked reduction in ileal substance P content and increased MPO activity, protein and nitrite secretion." (PMID 18475536, 1993). "In accordance, the therapeutic effect of GMP on MPO activity and intestinal damage extension in TNBS-induced ileitis has been reported." (PMID 32443501, 2020). "Increase MPO activity; no impact on the severity of ileitis." (PMID 35893902, 2022).